MUC1 (mucin 1, cell surface associated)
Diseases named in the same sentence as MUC1 in open-access papers (continued):
Sharing a sentence is not in itself a finding about the gene and the disease.
cancer (continued). "Finally, as a representative for O-glycoproteins, we chose a fragment of human mucin MUC1, one of the most complex glycoproteins in biological systems, which is also overexpressed with aberrant O-glycans in cancer, and a promising cancer biomarker and immunotherapeutic target." (PMID 37824645, 2023). "Moreover, when recombinant aldolase A was added to MUC1 silenced cancer cells, the adhesion rate of P. aeruginosa was similar to control values, suggesting that aldolase-mediated adherence of P. aeruginosa was, at least partly, independent of MUC1-mediated adhesion." (PMID 36609683, 2023). "SLea and SLex on MUC1 not only play a role in cancer cell adhesion and metastasis, but also compete with selectin ligands on leukocytes, interfering with their recognition and clearance of cancer cells, thereby helping cancer cells escape immune system surveillance." (PMID 37894512, 2023). "The function of MUC1 in cancer might change according to its intracellular localization." (PMID 37002293, 2023). "Finally, a possible mechanism by which MUC1 promotes cancer cell metastasis is related to anoikis." (PMID 37894512, 2023). "Furthermore, calcium carbonate NPs modified with mucin 1 (MUC1) dimer aptamers could also deliver epirubicin and MLT to cancer cells overexpressing MUC1 glycoproteins." (PMID 38017537, 2023). "Thus, blocking MUC1 with monoclonal antibodies can inhibit the interaction of mucin with neighboring receptors and suppress the ensuing induction of proper cellular signaling pathways, leading to cancer development." (PMID 37685842, 2023). "Therefore, most MUC1-C-associated cancers have not been subject to negative selection pressures that should be occurring with emergence of the MUC1 gene in mammals and chronic inflammation in humans." (PMID 36230728, 2022). "Moreover, the National Cancer Institute has declared MUC1 as a priority cancer antigen." (PMID 35806376, 2022). "However, little is known about whether and how MUC1 contributes to mitochondrial homeostasis in cancer cells." (PMID 36289190, 2022). "Besides, MUC1 has also been involved in therapeutic cancer vaccines in recent years." (PMID 35102706, 2022). "As the intracellular fragment of MUC1 has been shown to be trafficked to the nucleus and modulate transcription factors, the enhanced MUC1 endocytosis of hypo-glycosylated MUC1 in cancer cells may potentiate its oncogenic signaling by increasing its intracellular accumulations." (PMID 35654773, 2022). "Besides, MUC1 aptamers could be utilzied to modify DNPs to form conjugates, which can be used as fluorescent probes for cancer targeting and sensing, real-time imaging and drug release monitoring." (PMID 34425823, 2021). "Hence, MUC1-high expressing cancer cells can evade the extrinsic apoptosis pathway." (PMID 34681277, 2021). "Furthermore, Tmunity Therapeutics Inc. recently registered a phase I trial (NCT04025216) to test the safety, tolerability, feasibility, and preliminary efficacy of targeting the Tn glycoform of MUC1 (TnMUC1) using CAR-T cells in TnMUC1-positive advanced cancers, including NSCLC." (PMID 33025047, 2021). "However, in cancer cells, MUC1 often undergoes aberrant glycosylation and overexpression." (PMID 34207342, 2021). "Therefore, we hypothesized that a humanized version of a cancer-specific murine anti-MUC1 antibody can be used to activate NK cells for cancer immunotherapy." (PMID 34070311, 2021). "Consequently, anti-MUC1 Apt can be used for targeted drug delivery to cancer cells." (PMID 33499388, 2021). "In addition to regulating EMT, MUC1 promotes cancer progression through other mechanisms." (PMID 33060563, 2020).
cancer (continued). "However, MUC1 has been shown to play a paradoxical role following infections, acting as an anti-inflammatory molecule in healthy cells and as a pro-inflammatory molecule in cancer cells." (PMID 33167508, 2020). "Interestingly, MUC1‐specific cytotoxic T‐lymphocytes prompted clinical studies of MUC1‐targeting vaccines in PC, and a subsequent animal experiment revealed that MUC1 could provide immune protection against cancer cells in wild‐type mice." (PMID 32745356, 2020). "Therefore, it seems possible that MUC1 SNP rs4072037 could contribute to cancer development by influencing the gastric composition." (PMID 32733423, 2020). "MUC1 oncoprotein could also facilitate the pro‐adaptive stress response axis through cytidine deaminase‐mediated pyrimidine metabolic reprogramming and ROS alterations, therefore regulating cancer cell survival and chemotherapy response in PC." (PMID 32745356, 2020). "BI1361849 (CV9202) is an active cancer immunotherapeutic comprising protamine-formulated, sequence-optimized mRNA encoding six non-small cell lung cancer (NSCLC)-associated antigens (NY-ESO-1, MAGE-C1, MAGE-C2, survivin, 5T4, and MUC-1), intended to induce targeted immune responses." (PMID 30736848, 2019). "MUC1 is extensively glycosylated and the differences in antibody reactivity were found to be due to changes in the O-glycosylation of the serines and threonines in the TR domains of the cancer mucin where the glycans added were truncated and more heavily sialylated than in the normal epithelia." (PMID 29784646, 2018). "Thus, an sensitive detection of MUC1 is great importance in preliminary diagnosis of cancer." (PMID 35547495, 2018). "Engineered CAR T cells directed against MUC-1 could potentially represent a rationale for the investigation, in preclinical models, of cellular immunotherapy in LM, for future possible designs of immune-based cancer therapies." (PMID 28399903, 2017). "The mechanism by which Apt-Td enters the MUC1-positive cancer cells is currently unknown." (PMID 27203221, 2016). "MUC1 is able to modulate the Wnt signalling pathway through the formation of an intracellular complex with β-catenin, which is, in turn, capable of co-activating cyclin-D1 expression in the cell nucleus, ultimately promoting tumorigenesis by allowing cancer cells to avoid apoptotic pathways." (PMID 27409642, 2016). "However, the alterations in glycosylation patterns in cancer, as well as potential heterogeneity in the glycosylation patterns in cancer could complicate analyses of MUC1 expression in tissues and degrade its performance as a biomarker." (PMID 27846218, 2016). "In addition to highlighting the potential of these antibodies as future immunotherapeutics, detailed characterization of the humoral response to the MUC1 vaccine in a healthy individual aids in the overall analysis of a MUC1 prophylactic cancer vaccine potential." (PMID 27545199, 2016). "Thus, Muc1 is considered a valid target for cancer treatment." (PMID 26266422, 2015). "Unlike parental MUC1 that is present in both normal ovary and cancer cells, MUC1-TRIM46-KRTCAP2 chimeric RNAs are detected primarily in tumors, and thus may represent significantly better MUC1 variants for cancer detection using local biomaterials such as biopsy tissues." (PMID 26492273, 2015). "Identification of CIN85 and Cbl as binding proteins of MUC1 provides the mechanistic support for its functions as the promoter of cancer invasiveness and metastasis and suggests that drugs capable of breaking this complex might be effective at reducing metastatic potential of tumors." (PMID 25675408, 2015). "Furthermore, galectin-3 interacts with T antigens on MUC1 to promote cancer metastasis." (PMID 25762620, 2015). "Therefore, the overexpression of MUC1 may predict a more aggressive biological behavior in several types of cancers." (PMID 26667143, 2015).
cancer (continued). "The speculations on the role of MUC1, a substance which is overexpressed inglandular cancer cells, on the metastatic potential of such cells are rooted indata that seem to indicate that cell malignization correlates with a changefrom the apical localization of mucin MUC1 to a peripheral one." (PMID 25093113, 2014). "In addition to these genes, there were other genes that were of interest and associated with cancer development or progression including dimethylarginine dimethylaminohydrolase 1 (DDAH1), kinesin family member 3A (KIF3A), and MUC1 which are all upregulated in the poor prognosis samples." (PMID 24634783, 2014). "Moreover, because downregulation of MUC1 in cancer cells can inhibit cell migration by promoting the expression of the cell adhesion molecules E-cadherin and β-catenin, we also investigated the impact of GALNT3 knockdown on E-cadherin and β-catenin protein expression." (PMID 24504219, 2014). "Therefore, galectin-3 overexpression in cancer could possibly be related to the frequently observed intracellular retention of MUC1." (PMID 25261375, 2014). "In addition, recent reports demonstrated that the VNTR sequence found in the extracellular domain of MUC1 may carry altered O-glycophenotypes, which could be responsible to modulate cancer cell invasion and migration." (PMID 24724053, 2014). "Furthermore, the modification of MUC1 glycosylation in cancer cells may increase the capacity of DC to acquire this antigen for cross-presentation." (PMID 23509794, 2013). "Finally, we discuss MUC1-based immunotherapy clinical trials against cancers." (PMID 23509794, 2013). "Thus, we speculate that modifications in the Lewis y antigen are responsible for its influence on MUC1 in malignant tumors." (PMID 23708102, 2013). "This could be a potential pitfall for design of MUC1 targeting cancer vaccines." (PMID 23189185, 2012). "Therefore, MUC1 is widely accepted as an effective target for cancer immunotherapy." (PMID 23028615, 2012). "MUC1 is a transmembrane glycoprotein that is expressed in normal pancreas but overexpressed and aberrantly glycosylated in >90% of metastatic PDAC and its aberrant expression has been associated with increased metastasis and poor prognosis of PC and other cancers." (PMID 23102107, 2012). "The first method utilizes synthetic glycopeptides believed to exist on cancer MUC1, conjugation of these glycopeptides to create an immunogen, immunization of mice, collection of anti-sera, and analysis of the binding of antibodies to MUC1 expressed on cancer cells by flow cytometry (FACS) analysis." (PMID 23023583, 2012). "However, on many carcinomas, MUC1 is over-expressed and found on all cell surfaces." (PMID 24970145, 2012). "Thus, the requirement for MUC1 in vitro and in vivo could represent a general mechanism to drive the metastatic phenotype for carcinoma cells which are dependent upon EGF/EGFR/Src signaling." (PMID 22586492, 2012). "This provides new information into our understanding of the molecular mechanisms of cancer cell haematogenous dissemination and suggests that targeting the interaction of circulating galectin-3 with MUC1 in the circulation may represent an effective therapeutic approach for preventing metastasis." (PMID 20565834, 2010). "In cancer patients, MUC1 glycoprotein may carry Lewis y which could be involved in immune response." (PMID 19715603, 2009). "Further direct analyses are therefore required to determine whether MAL2 and MUC1 levels are positively correlated in cancer types commonly expressing these proteins, and whether MAL2 expression is significantly associated with cell surface expression of MUC1 in cancer cells." (PMID 19175940, 2009). "Thus, a new class of potent anti-cancer therapeutics could be designed around agents that interfere with the interaction between the extracellular domain of MUC1*1110 and its activating ligands." (PMID 18446242, 2008).
cancer (continued). "The aim of this study was to investigate the role of rs4072037 in relation to the alternative splicing events of MUC1, in both TR-containing and TR-negative transcripts, for a range of normal non-cancer tissues, to help evaluate published results and as a platform for future cancer studies." (PMID 19238635, 2008). "Recent evidence suggests that the induction of a strong anti-MUC1 response in cancer patients may require the activation of specific T helper cells via MHC class II presented peptide and glycopeptide epitopes, a process that is controlled by site-specific O-glycosylation." (PMID 12966437, 2003). "Single domain antibody-based MUC1-redirecting CAR-T has shown promise as an effective and low-immunogenic cancer immunotherapy approach." (PMID 40069884, 2025). "The MUC1 N-terminus is extracellular and consists of a variable number of 20 amino acid tandem repeat (VNRT) whose sequence changes in different cancers." (PMID 40001578, 2025). "Overall, our findings prove for the first time, that fisetin, an MUC1 inhibitor, is a highly effective treatment for OSCC cancer." (PMID 39926326, 2025). "In a different study, the Silica Immunoinformatics approach was used to construct a multifunctional vaccine for NSCC cancer that included MHC I, MHC II, CTL, and B-cell epitopes obtained from MAGE-A3 cells, EGF, and MUC-1." (PMID 40453095, 2025). "The current chapter shows the importance of various mucins (MUC1, MUC3A, MUC4, MUC4β, MUC5AC, MUC5B, MUC7, and MUC16) and their mucin-bound carrier proteins in different cancers." (PMID 40699805, 2025). "Recent pan-cancer analysis identifies CD155 as a promising target for CAR-T cell therapy, and identifies MUC1 as a pan-cancer target for drug development for a diverse array of solid tumors and hematological malignancies." (PMID 41294857, 2025). "The PANVAC vaccine utilizes a modified poxvirus vector to deliver the genetic instructions for these antigens to the immune system, with the aim of provoking an immune response that targets and eliminates cancer cells expressing CEA and MUC1." (PMID 40333213, 2025). "Previous studies have indicated that the C-terminus of MUC1 triggers Wnt/β-catenin pathway and increases SNAIL transcription to activate epithelial-mesenchymal transition (EMT) in cancer cells." (PMID 40996224, 2025). "The MUC1-HIF-1α signaling pathway is also able to regulate polyamine metabolism, a key survival pathway in cancer cells." (PMID 40001578, 2025). "MUC1 interacts closely with EGFR, which promotes cancer progression and influences therapeutic responses, significantly impacting the pathology NSCLC." (PMID 40655139, 2025). "Epitope-based cancer vaccines targeting TAAs, such as HER2, MUC1, CEA, and MAGE-A, have shown promise in preclinical and early clinical trials." (PMID 40333213, 2025). "In this regard, the high affinity interaction between Galectin-3 (Gal-3), a member of β-galactoside binding protein family, and T antigen, located on the MUC1, is fundamental for TME regulation and cancer." (PMID 40001578, 2025). "Cancer vaccines represent another immunotherapeutic approach that is being explored for the treatment of BTC, with studies focusing on WT-1 and MUC1 antigens." (PMID 40940908, 2025). "The immunosuppressive effects of MUC1 in the TME can also be mediated through its influence on other mucins and cancer-related pathways." (PMID 40655139, 2025). "MUC4, MUC1, and MUC16 are involved in the regional invasion and migration of cancer cells through various signaling pathways." (PMID 40699805, 2025). "Compared to other well-established cancer targets such as B7-H3 42, 43, EGFR 44-46 and MUC-1 47, S15 has rarely been exploited as an immune cell therapy target." (PMID 40365291, 2025). "This method achieved an LOD of 1.52 nM, exhibiting high sensitivity and selectivity, and was successfully applied for MUC1 detection in human serum samples and imaging of MCF-7 cancer cells." (PMID 40363817, 2025).
cancer (continued). "Our results are consistent with other studies that have developed multi-epitope vaccines targeting cancer antigens such as CEA, MUC1, and EGFR in CRC." (PMID 40599850, 2025). "MUC1 overexpression interferes with integrin-mediated cell adhesion to the ECM, increasing the invasiveness of cancer cells." (PMID 40443562, 2025). "The TG4010 vaccine utilizes a modified vaccinia Ankara carrier that expresses MUC1 and IL2, aimed at inducing an immune response against cancer." (PMID 40625850, 2025). "Two studies have demonstrated that synthetic glycopolymers, which truncate either MUC1 or MUC16, can reduce the glycocalyx density, thus slowing cancer development." (PMID 40443562, 2025). "Parallel to MUC1, the modulation of MUC16 expression has emerged as a key factor in augmenting the response of cancer cells to therapeutic interventions." (PMID 38361923, 2024). "This review examines the roles of MUC1 and MUC16 in cancer immune regulation and therapeutic effectiveness, exploring their potential in precision medicine." (PMID 38361923, 2024). "Following the confirmation of the aptamer’s targeting capability towards MUC1-positive cells, we gauged the selectivity of A-f-M13-MB for CTC capture by incubating it with various cancer cells for 30 minutes." (PMID 38992001, 2024). "Studies have shown that MUC1 can participate in epigenetic reprogramming, EMT, stemness, neuroendocrine (NE) phenotype, cancer stem cell (CSC) state and immunosuppression in PCa." (PMID 39491020, 2024). "Monoclonal antibodies against the MUC1 VNTR are powerful research tools with applications in the diagnosis and treatment of MUC1-expressing cancers." (PMID 38508723, 2024). "MUC1, MUC2, MUC5AC, and MUC6 were the most commonly analyzed mucins across cancer types according to this literature review." (PMID 39886661, 2024). "Recent clinical trials have highlighted MUC1 and MUC16’s significant potential as immunotherapy targets in advanced cancer treatment, particularly in various solid tumors." (PMID 38361923, 2024). "Regarding the immunomodulatory capacity of these proteins, MUC1 and MUC16 were found to mask TLR signaling, resulting in the reduction of effector T cell functions, therefore enhancing cancer cell immune evasion and metastasis." (PMID 39744399, 2024). "Furthermore, MUC1 activity could enhance glucose metabolism in cancer cells." (PMID 38540735, 2024). "In stage III and IV MUC1 positive OTSCC, 63.6% (21/33) and 48.5% (16/33) patients had a MUC1-positive cancer cell rate of more than 50% and 80%, respectively." (PMID 38390321, 2024). "Monoclonal antibodies against the MUC1 VNTR can be powerful tools because of their multiplicity of binding and possible applications in the diagnosis and treatment of MUC1-expressing cancers." (PMID 38508723, 2024). "Further exploratory analyses revealed that CTLA4, PDCD1, and the cancer antigens MSLN, MUC1, EPCAM, and PROM1 presented significantly increase expression levels in the high-risk subtype group." (PMID 39712016, 2024). "Kunkler and colleagues administered intravesical anti-MUC1 monoclonal antibody (mAb) NCRC48 to 12 patients with radiologically confirmed BCa, demonstrating increased uptake of NCRC48 in cancer tissue compared to normal mucosa." (PMID 39491020, 2024). "In a 2017 phase I trial, eight patients with various types of cancer, including PCA, who tested positive for PD-1 and mucin 1 (MUC1) were treated with CAR-NK cells that targeted both MUC1 and PD-1." (PMID 38801637, 2024). "In most tissues, Prominin-1 is partially co-expressed with cancer markers such as carcinoembryonic antigen (CEA) and mucin 1 (MUC1)." (PMID 39409917, 2024). "Of the MUC1-positive OTSCC patients in stages III and IV, 63.6% (21/33) and 48.5% (16/33) respectively had MUC1-positive cancer cell rates of over 50% and 80%, respectively." (PMID 38390321, 2024).